BAP1 (BRCA1 associated deubiquitinase 1)
Diseases named in the same sentence as BAP1 in open-access papers (continued):
Sharing a sentence is not in itself a finding about the gene and the disease.
melanoma (continued). "Dermoscopic and molecular findings aid in diagnosing melanoma in BAP1-TPDS, and clinicians should have a high index of suspicion and a low threshold for screening and diagnostic testing for cutaneous malignancies in these patients." (PMID 34646590, 2021). "Pathogenic variants in many other genes (including c-kit, MAGE-1, CDK4, BAP1, and BRCA2) have also been associated with melanoma." (PMID 33509032, 2021). "The overall contribution of recently identified CM predisposition genes (ACD, BAP1, POT1, MITF, and TERF2IP) to melanoma’s missing heritability is estimated to be about 2%." (PMID 32325837, 2020). "PUM spheroids underwent immunohistochemistry for melanoma markers, nuclear BAP1, and cell proliferation." (PMID 32832244, 2020). "Recent studies have led to the identification of new genes involved in CMM susceptibility: beyond CDKN2A and CDK4, BAP1, POT1, and MITF were recently identified as potential high-risk melanoma susceptibility genes." (PMID 33322357, 2020). "In 2015, a revision of the prevalence of mutations in susceptibility CMM genes reported that, in 2511 melanoma-prone pedigrees, the mutation prevalence was about 20% for CDKN2A, 0.7% for CDK4, 1% for BAP1, and 0.5% for POT1." (PMID 33322357, 2020). "After screening, we identified 3 genes, 26S proteasome non-ATPase regulatory subunit 14 (PSMD14), Ubiquitin-like protein 5 (UBL5), and BRCA1 Associated Protein 1 (BAP1), as DUBs related to melanoma growth." (PMID 33154524, 2020). "Numerous genes have been associated with melanoma: beyond CDKN2A and CDK4, primarily included as high-risk genes for familial melanoma, BAP1, POT1, and MITF were recently also identified as potential high-risk melanoma susceptibility genes." (PMID 33322357, 2020). "Of note, similar results were obtained for the BAP1 interactome in Uveal Melanoma MP41 cells, suggesting that BAP1.com composition is not cell-type dependent." (PMID 30664650, 2019). "Other studies reported that BRCA-associated protein 1 (BAP1) and protection-of-telomeres-1 (POT1) mutations, as well as multiple MC1R variants are also associated with MPM and familial melanomas." (PMID 31382929, 2019). "Unexpectedly, all of the samples expressed nBAP1, therefore we conclude that BAP1 IHC cannot be used for prognostication in canine melanoma." (PMID 30060843, 2018). "In order to confirm that BAP1 localized to the nuclei of canine melanoma cell lines, we used immunofluorescence." (PMID 30060843, 2018). "We investigated nBAP1 expression by IHC in a panel of canine melanoma samples from different anatomical sites; this was planned as a prelude to a study investigating the prognostic significance of BAP1 in canine melanoma." (PMID 30060843, 2018). "Together these data suggest that oral canine melanoma cell lines express nBAP1 protein, and that this anti-human BAP1 antibody can be used for IHC in canine melanoma tissue." (PMID 30060843, 2018). "We sequenced BAP1 in 1,977 melanoma cases and 754 controls and used deubiquitinase assays, a pedigree analysis, and a histopathological review to assess the consequences of the mutations found." (PMID 28062663, 2017). "Mutations of several ubiquitination‐associated enzymes, such as BAP1, FBXW7 and PARK2, can lead to melanoma tumorigenesis." (PMID 28544818, 2017). "Aside from BAP1, the genetic mutation of another ubiquitin ligase FBXW7 has also contributed to the tumorigenesis of melanoma." (PMID 28544818, 2017). "Loss of BAP1 was also associated with poor disease-free survival (DFS) and melanoma-specific survival (MSS) after adjusting for clinical and pathological factors in cutaneous melanoma." (PMID 28404968, 2017). "FNA confirmed melanoma with a mix of oval spindle and polyhedral epithelioid cells, and an inactivation of the BAP1 gene." (PMID 28487752, 2017). "Immunohistochemically, intact BAP1 protein expression was found in the tumor cell nuclei of this melanoma." (PMID 26769193, 2016).
melanoma (continued). "Germline CDKN2A mutations occur in 40 % of 3-or-more case melanoma families while mutations of CDK4, BAP1, and genes involved in telomere function (ACD, TERF2IP,POT1), have also been implicated in melanomagenesis." (PMID 26433962, 2016). "Recently, a role for BAP1 in primary melanoma of the CNS was suggested based on the identification of a BAP1 germline mutation in a patient with primary CNS melanoma with monosomy 3 and a family history of UM and meningioma." (PMID 26769193, 2016). "We performed genetic analysis of CDKN2A, CDK4, BAP1, MC1R, and MITFp.E318K in Danish high-risk melanoma cases and found CDKN2A germline mutations in 11.3% of CM families with three or more affected individuals, including four previously undescribed mutations." (PMID 25803691, 2015). "Germline mutations in additional genes were recently associated with melanoma occurrence: MITF, BAP1, TERT promoter, POT1, and MGMT." (PMID 26106605, 2015). "The higher rate of BAP1 alterations among CM patients from mixed CM-OM lineages compared to other hereditary melanoma patients (29% vs. 0.52%; p = .003)." (PMID 22545102, 2012). "An additional five BAP1‐inactivated melanomas were identified and included as controls." (PMID 39976080, 2025). "Importantly, the majority of BAP1‐inactivated melanomas (4/5) in this study had histopathologic features well outside of the spectrum of typical BIMs." (PMID 39976080, 2025). "The patients with BAP1‐inactivated melanomas averaged 54 years." (PMID 39976080, 2025). "BRCA1‐associaed protein‐1 (BAP1) inactivated tumours (BIMT) are rare melanocytic tumours that may be mistaken for Spitz tumours or melanoma." (PMID 39268598, 2025). "Beyond melanoma, Class II and III MAP2K1 mutations have been identified in spitzoid, WNT-activated, protein kinase-activated, and BAP1-inactivated tumours, but reports of MAP2K1-driven melanocytic neoplasms without additional molecular alterations are scarce, with limited clinical follow-up." (PMID 40107205, 2025). "In addition, BAP1 is essential in prostate cancer, small cell lung cancer, and mouse melanoma cell viability in vitro and in vivo." (PMID 39817454, 2025). "Inactivating BAP1 mutations were more prevalent in uveal (55%) compared to non-uveal (17%) melanomas." (PMID 38903495, 2024). "The purpose of this study was to perform a mutational analysis of the seven candidate melanoma susceptibility genes (ACD, BAP1, MC1R, MITF, POT1, TERF2IP, and TERT) in high-risk melanoma patients (familial melanoma and MPM) from southeastern Brazil, besides the CDKN2A and CDK4 genes." (PMID 37958811, 2023). "Some studies have suggested that BAP1 may play a role in the development and progression of melanoma." (PMID 37504268, 2023). "The precise role of BAP1 in melanoma is not yet fully understood." (PMID 37504268, 2023). "Subsequent investigations showed that WWP1 overexpression in melanoma cells could mediate K48-linked ubiquitination of KLF5 and induce its proteasomal degradation, whereas BAP1 overexpression reverted this modification and increased KLF5 protein expression." (PMID 36918822, 2023). "While hematopoietic-restricted BAP1 loss in mice has been reported to lead to myeloproliferative or MDS-like disease, somatic BAP1 mutations, unlike in some solid tumors (e.g., malignant mesothelioma and melanoma), are rarely present in myeloid malignancies." (PMID 36068610, 2022). "Here, we show that BAP1 loss leads to increased expression of PROS1 in uveal melanocytes and melanoma cells, which in turn leads to phosphorylation and activation of the receptor tyrosine kinase MERTK on adjacent macrophages, driving them into a suppressive M2-polarized state." (PMID 35954340, 2022).
melanoma (continued). "BAP1-inactivated melanocytic lesions exist in a spectrum that goes from benign melanocytic nevi, usually combined (“BAPomas”), to intermediate lesions with atypical features (akin to the atypical Spitz tumor) and ending with malignant melanoma." (PMID 35052351, 2021). "In conclusion, our study suggests that a BAP1-inactivated nevus, an atypical tumor, and melanoma with the same background from the same patient possess distinct gene expression profiles, with notable upregulation of genes involved in protein kinase pathways in the progression from nevus to melanoma." (PMID 35052351, 2021). "Besides presenting as a part of the familial cancer syndrome, BAP1-inactivated melanocytic tumors, including benign-appearing nevi, atypical tumors, and melanomas can also occur in a sporadic fashion." (PMID 35052351, 2021). "Two slow-growing UM cell lines XMP46 and MM28 (GNAQ/11-mutation, BAP1-negative) were not sensitive to VP, and neither were the two conjunctival melanoma cell lines (BRAF/NRAS-mutation)." (PMID 33798262, 2021). "In line with our initial observations, only a minority of the cases (12/125; 9.6%) could be explained by a clinically validated pathogenic variant in one of the two known genes predisposing to both melanoma and RCC, namely MITF (N = 9) and BAP1 (N = 3)." (PMID 34067022, 2021). "In addition, genes encoding protein tyrosine kinases, KIT and EPHA5, relevant receptors upstream of the MAPK pathway, are particularly highly expressed in the melanoma compared to BAP1-inactivated nevus." (PMID 35052351, 2021). "Interestingly, though the BAP1 protein associates with BRCA1, the data to support melanoma predisposition in carriers of either BRCA1 or BRCA 2 is mixed." (PMID 34638397, 2021). "Based on our analysis, activation of protein kinase pathways, especially the MAPK pathway, is largely observed in the atypical tumor and melanoma arising from BAP1-inactivated nevus compared to nevus, consistent with current knowledge of melanocytic progression." (PMID 35052351, 2021). "Further understanding of BAP1 network regulation in these melanomas may provide opportunities for future therapy." (PMID 32028647, 2020). "This study described opposite roles of BAP1 in survival of two types of melanoma patients." (PMID 32028647, 2020). "In the present study, a cohort of patients SPMs (n = 20) and MPMs (n = 19), sex-matched, was analyzed with our custom NGS panel that included 32 genes involved in melanoma susceptibility (e.g., CDKN2A, BAP1, POT1) and skin/hair pigmentation (e.g., TYR, TYRP1, OCA2)." (PMID 33748184, 2020). "As mutations in high-susceptibility genes greatly increase risk of melanoma development, individuals carrying CDKN2A, CDK4, BAP1, POT1, or MITF mutations should be educated on the importance of melanoma prevention and early detection and should undergo regular medical skin examination." (PMID 31717496, 2019). "In addition, strong to weak cytoplasmic BAP1 (cBAP1) expression was also seen in each case, consistent with the immunofluorescence data for canine melanoma cell lines." (PMID 30060843, 2018). "In this study we investigate the significance of BAP1 in canine melanoma." (PMID 30060843, 2018). "We initially focused the analysis to on variants in genes known to cause familial malignant melanoma, but we did not identify any clearly causative variation in these genes (BAP1, CDK4, CDKN2A, MC1R, MITF and PTEN)." (PMID 28623311, 2017). "Fine needle aspiration (FNA) confirmed melanoma with inactivation of the BAP1 gene." (PMID 28487752, 2017).
melanoma (continued). "In the case of melanoma, it would be pertinent to assess familial clusters, with sites which are manifested in CDKN2A and BAP1 mutation carriers, or whether the risks could be extended to as yet unknown cancer sites." (PMID 28198461, 2017). "Whilst two out of three of probands with a loss-of-function BAP1 variant had BAP-like histology in the proband’s melanoma, none of the remaining six cases classified as ‘predicted deleterious’ had such features (not shown)." (PMID 28062663, 2017). "BAP1 showed predominantly nuclear localization in melanoma cells with wild type BAP1." (PMID 28404968, 2017). "The median age at diagnosis of melanoma was 57 years in cases carrying no variant or a benign variant in BAP1, compared to 49 years in cases within the ‘predicted deleterious’ group." (PMID 28062663, 2017). "The presence of suggestive histological features (‘BAP-like histology present (in the proband’s melanoma)’), however, was not significantly predictive of a predicted deleterious BAP1 variant compared to no variant (P = 0.1)." (PMID 28062663, 2017). "Taken together, the deubiquitinase BAP1 could be considered as a promising prognostic biomarker in melanoma." (PMID 28544818, 2017). "Other high-risk melanoma genes have been discovered: cyclin-dependent kinase 4 (CDK4), BRCA-1 associated protein (BAP1), and recently via exome sequencing of dense melanoma families, several new high-risk genes affecting telomere functions have been identified: POT1, ACD, TERF2IP and TERT." (PMID 25803691, 2015). "Thus, MM patients carrying germline BAP1 mutations benefit from this information, and their relatives may benefit from screening programs for early cancer detection, when these malignancies can be cured by resection (melanomas) or are more susceptible to therapy (MM and other cancers)." (PMID 26683624, 2015). "Additionally, this study is not a complete survey of all of the genes thought to confer an increased familial melanoma risk and the screening for germ-line mutations in CDKN2A, p16, ARF, CDK4, and BAP1 was incomplete." (PMID 23825798, 2013). "Regardless, the low rate of somatic BAP1 alterations itself in sporadic CM along with the rarity of the characteristic NEMMP and nevoid melanoma lesions in the general melanoma population suggest that BAP1 mutagenesis is linked to a restricted carcinogenic pathway in melanocytes." (PMID 22545102, 2012). "Taken together, the precise targets that drive melanoma progression in the face of BAP1 loss are not known though widespread effects in many diverse pathways are likely given the role of ubiquitination in the maintenance of genetic homeostasis." (PMID 22545102, 2012). "Thus, the spectrum of tumorigenesis from highly atypical NEMMPs to nevoid melanomas appears to be a unique property of BAP1-mediated cutaneous carcinogenesis." (PMID 22545102, 2012). "Such approaches could help standardize risk stratification and improve reproducibility across experts, supporting the MTB in distinguishing lesions with intermediate biological potential, such as atypical Spitz tumors or BAP1-inactivated melanocytic tumors, from true melanomas." (PMID 41301061, 2025). "On the other hand, germline mutations in CDK4 or in the DNA repair genes BAP1 (BRCA1 associated protein-1), APEX1 (apopurinic/apurinic-endodeoxyribonuclease 1) or even TERT-linked gene (TERT, POT1, ACD, TERF2IP) mutations may also predispose to melanoma." (PMID 40361349, 2025). "Notably, BAP1 exhibits deubiquitinating activity toward a range of substrates, including histones, and is recognized as a multifunctional protein in various cancers such as melanoma." (PMID 41362702, 2025). "The cytoplasmic expression of BAP1 in this melanoma is a finding of unknown significance." (PMID 39268598, 2025).
melanoma (continued). "BAP1-inactivated melanocytic nevi/tumours that are clinically suspicious for melanoma following assessment by a dermatologist should be excised, Pre-emptive excision of all BAP1-inactivated melanocytic nevi/tumours may not be feasible, and the benefit of this approach remains unclear." (PMID 37607989, 2023). "This noncutaneous melanoma does not have an association with BAP1 gene mutations or deletions." (PMID 38090659, 2023). "Moreover, we detected single nucleotide transitions in ARID1A, ARID2, SMARCA4 and BAP1, all genes which have not been associated before with CNS metastases of melanomas." (PMID 33578810, 2021). "However, upfront tumor testing for BAP1 inactivation may have aided with prognostication and introduction of timely screening for melanoma and other malignancy." (PMID 34504799, 2021). "BAP1 mutation may occur as the driver genetic event in low CSD melanoma, but there is not a specific relation with sun—damage reported for the new category of BAP1-inactivated lesions." (PMID 35052351, 2021). "Indeed, mutations in the deubiquitinating enzyme BRCA1-associated protein 1 (BAP1), in the E3 ligase (or E3 ligase complex) Parkinson protein 2 (PARK2), and in the F-box and WD repeat-containing 7 protein (FBXW7), were shown to favor melanoma development." (PMID 33800394, 2021). "This melanoma had a Breslow thickness of 1.5mm, without evidence of ulceration, and it resembled the reported features of melanocytic lesions found in BAP1 mutation carriers, being distinctly dermal in silhouette and composed of pleomorphic, epithelioid melanocytes." (PMID 28062663, 2017). "None of the remaining six probands with BAP1 variants, predicted to be deleterious by SIFT or PolyPhen-2, had suggestive histology and importantly, similar histological changes were seen in a significant proportion of melanoma patients without a germline BAP1 mutation." (PMID 28062663, 2017). "Additionally, DNA methylation levels at the promoter regions of BAP1, MITF, and PALB2 genes were statistically associated with the number of melanomas presented by the individual and a hypermethylation of POT1 promoter was associated with Breslow thickness of the tumors." (PMID 26106605, 2015). "Furthermore, it may provide novel directions for the clinical treatment of BAP1-mutant melanoma." (PMID 39587076, 2024). "BAP1 counteracts WWP1-mediated KLF5 ubiquitination, promoting melanoma development by stabilizing KLF5 within the BAP1/HCF-1 complex." (PMID 39949609, 2024). "The pipeline identified variation in known germline melanoma genes POT1, MITF and BAP1 in 4 out of 13 families (31%)." (PMID 38866901, 2024). "Cluster 3 comprises the other, BAP1-positive, UM cell lines (92.1, MEL270, and OMM1) and melanoma cell line (OCM3)." (PMID 33798262, 2021). "That report also noted those cases to be metastatic and, similar to BAP1, posed the question of differential roles of SF3B1 depending on the type of melanoma cells." (PMID 32429485, 2020). "Additionally, pigmentation disorders also ranked at the top of the Human Phenotype Ontology database among BAP1-correlated genes for NHM and melanoma tumors." (PMID 41480773, 2026). "Conversely, adipocytic metaplasia has been suggested to be lacking in BAP1‐inactivated melanomas, possibly making this a relevant histologic feature." (PMID 39976080, 2025). "Among the 161 CDKN2A/CDK4/BAP1-negative melanoma families included in this cohort, only one likely PV in POT1 (c.676C > A, p.His226Asn) was identified (0.6%)." (PMID 40851494, 2025). "Among other established melanoma‐related genes that were included in our 360 gene panel and found negative in all index individuals were BAP1, TERT, and MITF." (PMID 40072281, 2025). "BAP1 alterations stood out in kidney (9.9%) and cervix (2.9%) cancers, with ATM most frequent in bladder cancer (7.7%), CDK12 notable in prostate cancer (7.4%), and FANCA prominent in melanoma (3.1%)." (PMID 40420266, 2025).